PGR (progesterone receptor)
Diseases named in the same sentence as PGR in open-access papers (continued):
Sharing a sentence is not in itself a finding about the gene and the disease.
breast cancer (continued). "Currently, breast cancer is classified into different subtypes according to the expression levels of hormone receptors (HRs) estrogen receptor (ER) and progesterone receptor (PR), and human epidermal growth factor receptor-2 (HER-2)." (PMID 38068930, 2023). "The widely-used diagnosis kit and mature detective technology have made PgR a highly reproducible assay for breast cancer subtypes." (PMID 36717797, 2023). "Breast cancer is classified according to the expression of the estrogen receptor (ER), the progesterone receptor (PR), and human epidermal growth factor-2 (HER2) receptors based on immunohistochemical staining." (PMID 36836059, 2023). "Breast cancer prognosis and management for both men and women are reliant upon estrogen receptor alpha (ERα) and progesterone receptor (PR) expression to inform therapy." (PMID 37940649, 2023). "Levels of estrogen receptor (ER), progesterone receptor (PR) and epidermal growth factor receptor 2 (Her-2) are gold standards for predicting survival and treatment responses in human breast cancer patients." (PMID 36693957, 2023). "In this study, we have comprehensively analyzed the relationship between the expressions of estrogen (ER), progesterone (PgR), and androgen receptors (AR), and the immunological profile in breast cancer." (PMID 36721218, 2023). "The results indicated that the changes in the culture medium Chol levels affected only human breast cancer cells that express ER and PgR and therefore respond to hormone therapy." (PMID 36983016, 2023). "Breast cancers are divided into four major phenotypic groups based on the presence or absence of key biological markers, namely estrogen receptor (ER), progesterone receptor (PR), and human epidermal growth factor receptor 2 (HER2)." (PMID 36672351, 2023). "Estrogen receptor (ER), progesterone receptor (PR) and epidermal growth factor receptor (Her2) on tumor cell surfaces are the main targets for therapeutic treatment of breast cancer." (PMID 37296887, 2023). "The status of hormone receptors (HR) including estrogen receptor (ER) and progesterone receptor (PR) is known to be correlated with response to endocrine therapy in breast cancer." (PMID 37444546, 2023). "Approximately 70–80% of breast cancers are considered hormone-dependent due to expression of the estrogen receptor (ER) and/or progesterone receptor (PR)." (PMID 37395895, 2023). "Ultimately, we found high TRIP6 mRNA levels in progesterone receptor-positive breast cancer and samples resected from premenopausal women." (PMID 36833223, 2023). "The intrinsic breast cancer typing is based on the expression of estrogen receptor (ER), progesterone receptor (PR), HER2/neu, and Ki67-labeling index." (PMID 37425505, 2023). "Breast cancer is characterized by the presence or absence in the cells of three targetable markers, estrogen receptor (ER), progesterone receptor (PR), and/or human epidermal growth factor receptor 2 (HER2)." (PMID 37686097, 2023). "Within breast cancer cells, three markers—estrogen receptor (ER), progesterone receptor (PR), and human epidermal growth factor receptor 2 (HER2)—are often used to determine the existence and concentration of cancer cells." (PMID 38248392, 2023). "HR+ breast cancers, primarily driven by estrogen receptor (ER) and/or progesterone receptor (PR) are amenable to endocrine therapies." (PMID 37954074, 2023). "Some of these proteins, such as HER2, ER, PGR are involved in key-regulatory mechanisms of breast cancer progression." (PMID 37741974, 2023). "Among patients with breast cancer, 301 897 (82.9%) were estrogen receptor (ER) positive and 264 768 (72.7%) were progesterone receptor positive." (PMID 37436746, 2023). "Treatment strategies for breast cancer subtypes are determined by the tumor expression status of estrogen receptor (ER), progesterone receptor (PgR) and human epidermal growth factor receptor 2 (HER2)." (PMID 36977973, 2023).
breast cancer (continued). "In POETIC 4480 postmenopausal patients with primary ER and/or PgR + breast cancer were randomised 2:1 to 2 weeks’ presurgical AI (anastrozole or letrozole) or no presurgical treatment (control)." (PMID 37046348, 2023). "As a hormone related cancer type, the subtype of breast cancer classification is based on the expression of three major factors: estrogen receptor (ER), progesterone receptor (PR) and human epidermal growth factor receptor 2 (HER2)." (PMID 36968583, 2023). "Breast cancer is classified into four subtypes according to estrogen receptor (ER), progesterone receptor (PR), and human epithelial growth factor receptor 2 (HER2) expressions." (PMID 38001620, 2023). "Breast cancer can be classified based on the expression status of estrogen receptor (ER), progesterone receptor (PGR), human epidermal growth factor receptor 2 (HER2), and Ki67." (PMID 37885013, 2023). "Breast cancer is a heterologous disease initially subcategorized as a function of receptor expression with respect to ER, progesterone receptor (PR) and human epidermal growth factor 2 (HER2) receptors." (PMID 37306503, 2023). "Triple-negative breast cancer (TNBC), a highly aggressive subtype of breast cancer, negatively expresses estrogen receptor, progesterone receptor, and the human epidermal growth factor receptor 2 (HER2)." (PMID 37641116, 2023). "First, we orthotopically transplanted estrogen and progesterone receptor–positive (ER/PR+) breast cancer line MCF-7 and triple-negative breast cancer (TNBC) line SUM-159 labeled with firefly luciferase (ffLuc) to NSG mice." (PMID 36989357, 2023). "PgR is a binding partner and major modifier of ER-mediated processes, suggesting its additional role in breast cancer other than its identification as an ER activity marker." (PMID 36721218, 2023). "Ninety-eight patients were found to have hormone-positive (either estrogen receptor [ER] or progesterone receptor [PR} receptor) breast cancer." (PMID 37265920, 2023). "The classification of breast cancers is based on the expression levels of the following specific markers: estrogen receptor (ER), progesterone receptor (PR), human epidermal growth factor receptor-2 (HER2), and the Ki-67 index." (PMID 37860188, 2023). "Human epidermal growth factor receptor 2 (HER2), which determines histopathological molecular subtypes along with estrogen receptor (ER) and progesterone receptor (PR), is an important indicator for the treatment and prognosis of breast cancer." (PMID 36346486, 2023). "The RAC3 gene was amplified in breast cancer and correlated with tumor size and estrogen as well as progesterone receptor positivity." (PMID 36936912, 2023). "The 6 tumors were characterized with the most important and frequent biomarkers of breast cancer: estrogen receptor (ER), progesterone receptor (PR), and HER2." (PMID 36737789, 2023). "Progesterone-induced modification of the progesterone receptor and estrogen receptor genomic binding pattern is also involved in orchestrating estrogen signaling in breast cancer, preventing cell migration and invasion, and improving patient outcomes." (PMID 37395734, 2023). "All patients in this study had luminal breast cancer tumors, characterized as estrogen receptor-positive, progesterone receptor-positive, human epidermal growth factor receptor 2 (HER2)-negative, and low levels of KI-67 expression." (PMID 37511584, 2023). "Breast cancers can be categorized into three major subtypes on the basis of the hormone receptors: estrogen receptor (ER) positivity, progesterone receptor (PR) positivity and human epidermal growth factor 2 (HER2, also known as ERBB2) positivity." (PMID 38052873, 2023). "Molecular sub-typing of breast cancer heavily relies on the expression patterns of estrogen receptor (ER), progesterone receptor (PR) and human epidermal growth factor receptor 2 (HER)." (PMID 37491277, 2023).
breast cancer (continued). "A total of 612 patients (85.7%) were positive for ER, 398 patients (55.4%) were positive for PgR, and 621 patients (86.3%) were classified as having HR+ breast cancer, which represented the majority of cases." (PMID 36894884, 2023). "Triple-negative breast cancer (TNBC), a type of breast cancer where estrogen receptor (ER), progesterone receptor (PR), and Her-2 are expressed at a low level, has the highest malignancy and worst breast cancer prognoses." (PMID 37342347, 2023). "Older women are more likely to have estrogen receptor-positive (ER+) and progesterone receptor-positive (PR+) breast cancer than younger women." (PMID 37020865, 2023). "Breast cancer is most commonly classified based on the molecular subtypes, which are dependent on the molecular profiles of the estrogen receptor (ER), progesterone receptor (PR), and human epidermal growth factor recpetor (HER2)." (PMID 36836779, 2023). "Overall, 61.5% of patients were oestrogen-receptor-positive at the time of breast cancer diagnosis (1406/2287—19 studies) and 51.5% were progesterone-receptor-positive (1050/2037—15 studies)." (PMID 37108278, 2023). "Numerous molecular markers already discovered and are known to affect breast cancer outcomes include Estrogen Receptor (ER), Progesterone Receptor (PR) from the steroid hormone receptor pathway and human epidermal growth factor in the HER family." (PMID 37580469, 2023). "In the case of breast cancer, positive PgR levels have shown to be more predictive of tumor response to hormonal therapy than ER levels." (PMID 36835012, 2023). "Breast cancer can be categorized into molecular subtypes by genetic information including the status of estrogen receptor (ER) and progesterone receptor (PR) and human epidermal growth factor receptor 2 (HER2)." (PMID 37064130, 2023). "Two crucial molecules for evaluating breast cancer heterogeneity and the advantages of hormonal therapy are the steroid hormone receptor ER and the progesterone receptor PR." (PMID 38049758, 2023). "Most breast cancer cells are estrogen receptor- (ER)/progesterone receptor (PR)-positive, with human epidermal growth factor receptor 2 (HER2)-negative (69%), and almost half of postmenopausal patients have ER-positive breast cancer cells." (PMID 36831555, 2023). "Although the relationship was not statistically significant, metastases tended to be found in PgR-positive breast cancer cases (p = 0.063)." (PMID 36894884, 2023). "Pathological analysis defined the breast cancer tissue as estrogen receptor (ER), progesterone receptor (PR), and human epidermal growth factor receptor 2 (HER2) positive (+) or negative (−)." (PMID 36527735, 2023). "Triple-negative breast cancer (TNBC) is a highly aggressive subtype of breast cancer that lacks the expression of estrogen receptor (ER), progesterone receptor (PR) and human epidermal growth factor receptor-2 (HER2)." (PMID 36813923, 2023). "Triple‐negative breast cancer (TNBC) is characterized by deficiency in estrogen receptor (ER), progesterone receptor (PR) and human epidermal growth factor receptor 2 (HER2) expression and represents one of the most aggressive subtypes of breast cancer." (PMID 37558205, 2023). "Patient 1, 54 years old, was diagnosed with estrogen receptor (ER–)/progesterone receptor (PR‒)/HER2+++ locally advanced (T4bN0M0) breast cancer in August 2019." (PMID 38213542, 2023). "Breast cancer subtypes are generally classified into estrogen receptor positive (ER+), progesterone receptor positive (PR+), human epidermal growth factor receptor 2 positive (HER2+), and triple-negative." (PMID 37836626, 2023). "Triple-negative breast cancer (TNBC), approximately 15% of invasive breast cancers, is the most aggressive breast cancer subtype; it lacks estrogen receptor (ER) expression, progesterone receptor (PR) expression, and HER2 gene amplification." (PMID 37226243, 2023).
breast cancer (continued). "Breast cancers are typically characterized based on the expression of three tumor markers, namely estrogen receptor (ER), progesterone receptor (PR), and human epidermal growth factor receptor (HER2)." (PMID 37190208, 2023). "Recently, the ASCO/CAP guideline for estrogen and progesterone receptor testing in breast cancer was updated." (PMID 37846186, 2023). "Seventy-nine (4.9%) women had a diagnosis of breast cancer, with 67/79 (84.8%) being estrogen or progesterone receptor positive." (PMID 37494669, 2023). "The primary subtypes of breast cancer are determined by protein expression levels of estrogen receptor alpha (ERα), progesterone receptor (PR), and human epidermal growth factor receptor 2 (HER2)." (PMID 36926316, 2023). "Endocrine therapy, commonly used to treat estrogen receptor–positive and progesterone receptor–positive breast cancers, and HER2-targeted therapies, used to treat HER2-positive breast cancers, are ineffective against TNBC." (PMID 36831368, 2023). "About 70% of patients with breast cancer are estrogen receptor (ER) positive and/or progesterone receptor (PR) positive." (PMID 37483519, 2023). "Luminal-like breast cancer includes luminal A- and B-like subtypes, characterized by expression of estrogen- (ER) and/or progesterone-receptor (PR)." (PMID 38036573, 2023). "Progesterone receptor (PgR): The progesterone receptor (PgR), regulated by estrogen, is another significant biomarker in breast cancer molecular diagnosis." (PMID 37627192, 2023). "In this study, we systematically analyzed the relationship between the expression of sex steroid hormone receptors such as ER, PgR, and AR and the immunological profiles of breast cancer tissues." (PMID 36721218, 2023). "In human breast cancer, ~ 50–70% of patients have high expressions of both estrogen receptor and progesterone receptor, representing a hormone-dependent cancer type, called luminal subtype." (PMID 37081505, 2023). "Based on immunohistochemistry analysis, breast cancer can be classified into three distinct molecular subtypes, including estrogen or progesterone receptor positive (ER+/PR+), human epidermal growth factor receptor positive (HER2+), and triple-negative (TNBC)." (PMID 37397367, 2023). "PRLR, encoding the receptor for prolactin (which is also called luteotropin, and has been described as the third hormone in breast cancer) resembles ESR1 more than PGR in our study." (PMID 37789381, 2023). "Immunohistochemical evaluation of estrogen receptor, progesterone receptor, and human epidermal growth factor receptor-2 status stratify the different subtypes of breast cancer and define the treatment course." (PMID 36769215, 2023). "It is widely known that breast cancer is classified into different subtypes according to ER, PR (progesterone receptor), and HER2 (human epidermal growth factor receptor 2) status." (PMID 36860312, 2023). "In contrast to previous studies on human breast cancer, we observed a higher frequency of PIK3CA mutations in patients with low ESR1 and PGR expression." (PMID 38033642, 2023). "Luminal B breast cancers are usually either estrogen receptor-positive and/or progesterone receptor-positive with high proliferation of Ki67 index, or HER2 positive (HER2+)." (PMID 37653831, 2023). "Luminal A and luminal B are hormone receptor (HR, estrogen, and/or progesterone receptor)-positive and are the most common subtypes, accounting for around 50–60% and 15–20% of the total breast cancer cases, respectively." (PMID 36831644, 2023). "Roughly 65% of patients develop hormone receptor–positive (HR+) breast cancer, characterized by the presence of estrogen receptor (ER) and/or progesterone receptor (PR)." (PMID 37440925, 2023). "We performed an immunohistochemical analysis of the expression of the breast cancer markers ER, PgR, HER2, and PD-L1 in the FFPE specimens." (PMID 36494460, 2023).
breast cancer (continued). "Steroid hormone receptors are crucial biomarkers in breast cancer, which including estrogen receptor (ER) and progesterone receptor (PR)." (PMID 38049758, 2023). "Human epidermal growth factor receptor-2 (HER2), estrogen receptor (ER), and progesterone receptor (PgR) are used to stratify breast cancer patients who respond to anti-HER2 antibody (trastuzumab) or hormone therapy." (PMID 36836537, 2023). "Triple-negative breast cancer (TNBC), one subtype of breast cancer, lacks progesterone receptor (PR), estrogen receptor (ER), and human epidermal growth factor receptor 2 (HER2)." (PMID 37953789, 2023). "It is known to all that the hormone receptor (HR) status, such as estrogen receptor (ER) and progesterone receptor (PR), play important roles in prognostic and treatment in breast cancer." (PMID 38125697, 2023). "Basal-like breast cancer largely overlaps with triple-negative breast cancer, which lacks ER and progesterone receptor (PR) expression and HER2 overexpression." (PMID 37943878, 2023). "The treatment outcome of breast cancer is closely related to estrogen receptor (ER), progesterone receptor (PR), and human epidermal growth factor receptor 2 (HER2) expression." (PMID 37275874, 2023). "Based on the expression of human epidermal growth factor receptor-2 (HER-2), and the two hormone receptors - estrogen receptor (ER) and progesterone receptor (PR), breast cancer is subcategorized into five subtypes." (PMID 36619229, 2023). "According to the expression of hormone receptors, we call a type of breast cancer that lacks the expression of estrogen receptor (ER), progesterone receptor (PR) and human epithelial growth factor receptor 2 (Her-2) as triple negative breast cancer (TNBC)." (PMID 37397391, 2023). "Breast cancer is divided into subtypes depending on hormone receptor (estrogen receptor [ER] and progesterone receptor [PgR]) and human epidermal growth factor receptor 2 (HER2) expression." (PMID 37051545, 2023). "Three breast cancer subtypes have been defined based on widely available biomarkers: estrogen receptor (ER), progesterone receptor (PR), and/or human epidermal growth factor receptor 2 (HER2)." (PMID 36669993, 2023). "Around 70% to 80% of patients with breast cancer have hormone receptor–positive (HR+) disease—meaning that their tumors express ER and/or progesterone receptor (PgR)—and most of these have ER-driven tumors at diagnosis." (PMID 37725704, 2023). "In breast cancer, biomarkers such as ER (estrogen receptor), PR (progesterone receptor), and HER2 (human epidermal growth factor receptor 2) are utilized for the identification of intrinsic subtypes." (PMID 37685875, 2023). "About 70% of all breast cancers express the estrogen receptor (ER), the progesterone receptor (PR), or both." (PMID 37046675, 2023). "Endocrine therapy by blocking the hormone receptor activities has been proven effective to treat breast cancer with the presence of estrogen receptor (ER) and/or progesterone receptor (PR)." (PMID 37095176, 2023). "Triple-negative breast cancer (TNBC) is a subtype of breast cancer that lacks expression of estrogen receptor, progesterone receptor, and human epidermal growth factor receptor 2 (HER2)." (PMID 36831368, 2023). "HLBC tumors were smaller than SEER-documented ILC tumors (median 1.40 vs. 2.00 cm; p = 0.002) and had a higher incidence of background lobular carcinoma in situ (88% vs. 1%; p < 0.001) as well as progesterone receptor positivity (95% vs. 81%, p = 0.032)." (PMID 37758801, 2023). "For therapeutic and prognostic purposes, breast cancer (BC) is often classified on the basis of oestrogen receptor (ER), progesterone receptor (PR) and human epidermal growth factor receptor-2 (HER2) expression." (PMID 37012444, 2023). "The stratification of breast carcinoma involves histological features, including the expression of markers such as estrogen receptor (ER), progesterone receptor (PR), and human epidermal growth factor receptor 2 (hEGFR2)." (PMID 37492478, 2023).